PCDHA5 (protocadherin alpha 5)
Description:
Potential calcium-dependent cell-adhesion protein. May be involved in the establishment and maintenance of specific neuronal connections in the brain.
Synonyms: CNRS6; CNR6; CRNR6; CNRN6; PCDH-ALPHA5
Tractability: Antibody: its Gene Ontology location is reachable by antibodies, with high confidence; UniProt places it where antibodies can reach, with medium confidence; UniProt predicts a signal peptide or a membrane-spanning region; the Human Protein Atlas places it where antibodies can reach.
Gene: Protein-coding gene on chromosome 5 (140,821,604 to 141,012,347, forward strand). Ensembl gene ENSG00000204965.
Subcellular location: Cell membrane
Subcellular location (Human Protein Atlas): Plasma membrane; Mitochondria; Nuclear speckles
Gene Ontology:
Molecular function: cell adhesion molecule binding; calcium ion binding
Biological process: cell adhesion; nervous system development; homophilic cell-cell adhesion
Cellular component: plasma membrane; membrane
Genetic constraint (gnomAD): Loss-of-function variants: 43 observed, 63.88 expected, observed/expected ratio (o/e) 0.67, 90% interval 0.53 to 0.87. The upper end of that interval is the gene's LOEUF score, 0.87, which puts it in group 3 of 6, group 1 being the genes least tolerant of losing a copy. Missense variants: 1,298 observed, 1,289.6 expected, observed/expected ratio (o/e) 1.01, 90% interval 0.96 to 1.05. Synonymous variants: 627 observed, 573.56 expected, observed/expected ratio (o/e) 1.09, 90% interval 1.02 to 1.17.
Homologues: Orthologues: mouse Pcdha5 (87% identical). Paralogues in human: PCDHA4 (83% identical), PCDHA8 (83% identical), PCDHA1 (82% identical), PCDHA3 (82% identical), PCDHA6 (82% identical), PCDHA2 (82% identical), PCDHA7 (82% identical), PCDHA13 (81% identical), PCDHA10 (81% identical), PCDHA9 (81% identical), PCDHA11 (80% identical), PCDHA12 (80% identical), and 49 more.
Diseases named in the same sentence as PCDHA5 in open-access papers:
PCDHA5 is named in the same sentence as 5 diseases in open-access papers, as found by Europe PMC text mining. Sharing a sentence is not in itself a finding about the gene and the disease. The quoted sentences say what the papers report.
schizophrenia (1 paper, 2021). A major psychotic disorder characterized by abnormalities in the perception or expression of reality. "Subsequently, we tested the effects of HSV-1 infection on the expression of schizophrenia-associated protocadherins PCDHA2, PCDHA3 and PCDHA5 given their identification in cell adhesion biological processes in our earlier analysis." (PMID 34859219, 2021). "We found that schizophrenia-associated members of the clustered protocadherin family PCDHA2, PCDHA3 and PCDHA5 were downregulated by MIA and mapped to the cell adhesion biological processes." (PMID 34859219, 2021). "Additionally, we showed that schizophrenia-associated protocadherins PCDHA2, PCDHA3 and PCDHA5 were downregulated in a dose-dependent manner in neuronal precursor cells following HSV infection." (PMID 34859219, 2021).
PCDHA5 also shares sentences with these, for which no sentence is quoted: bipolar affective disorder (1 paper); cancer (1); neurodevelopmental disorder (1); Usher syndrome type 1 (1).